CD4 (CD4 molecule)
Diseases named in the same sentence as CD4 in open-access papers (continued):
Sharing a sentence is not in itself a finding about the gene and the disease.
latent infection (continued). "To further determine whether TIQ-15 inhibits HIV-1 latent infection of blood resting CD4 T cells, we purified human resting T cells from peripheral blood (98% pure), and pretreated cells with TIQ-15, and then infected cells with HIV-1(NL4-3)." (PMID 39146384, 2024). "In addition, latent infection was elevated upon IEC stimulation of resting CD4 + T cells, whereas in activated CD4 + T cells, IEC stimulation enabled latent reservoir formation." (PMID 37202790, 2023). "However, HIV can persist throughout the body in cellular reservoirs partly due to the inability of some ARVs to cross anatomical barriers and the capacity of HIV-1 to establish latent infection in resting CD4+ T cells and monocytes/macrophages." (PMID 36831153, 2023). "In this study, we decided to examine whether activated CD4 + T cells would harbor latent infection after IEC stimulation." (PMID 37202790, 2023). "We chose to infect activated CD4 + T cells on later days post-activation (on day 7 rather than on day 3 peak activation) because there was a study showing infection on later days post-activation generated more latent infection." (PMID 37202790, 2023). "In the original model of latent infection of CD4+ T cells, latently infected cells were hypothesized to arise from infected activated cells as the cells returned to an immunologically resting state." (PMID 37733443, 2023). "We wanted to know whether IEC stimulation would result in latent infection of resting CD4 + T cells, as the gut mucosal tissue was found to be a major site for HIV latent reservoir." (PMID 37202790, 2023). "However, HIV-1 is able to infect and develop a latent infection in CD4+ T cells, establishing a stable viral reservoir in memory CD4+ T cells." (PMID 35891551, 2022). "We confirm and extend our previous observations from latent M. tuberculosis infection, demonstrating that distinct, M. tuberculosis–specific IL-22–producing CD4+ T cells contribute a substantial portion to the total CD4+ T cell response to M. tuberculosis in both latent infection and TB disease." (PMID 35777848, 2022). "First, the use of the dual-fluorescent virus could underestimate the frequency of latent infection in resting CD4+ T cells in vitro due to the poor constitutive expression of EF1α promoter in resting CD4+ T cells." (PMID 35499323, 2022). "In addition, studies using dual reporter viruses have demonstrated that chemokine treated resting CD4 T cells can support both productive and latent infection and that the majority of integrated virus becomes latent shortly after infection." (PMID 35895672, 2022). "Immune reconstitution syndrome (IRIS) is a state of unusual hyperinflammatory response against latent infections which occurs after CD4 cell count improvement and as a consequence of immune response once highly active antiretroviral therapy for HIV is introduced." (PMID 35321085, 2022). "Our discovery of the anti-HIV activity of CD2 signaling may offer new therapeutics to prevent HIV latent infection of blood CD4 T cells." (PMID 34765923, 2021). "We further tested whether prestimulation of resting CD4 T cells with the soluble CD2 ligand CD58 (LFA-3) can also block HIV-1 latent infection of resting CD4 T cells." (PMID 34765923, 2021). "Indeed, our data show that the dominant CD4 T-cell subset generated during latent infection is TH1 cells." (PMID 35186781, 2021). "Prestimulation of resting CD4 T cells with anti-CXCR4 antibody enhances HIV-1 latent infection of resting CD4 T cells; it has been shown that such stimulation leads to the activation of cofilin and localized actin activities, thereby facilitating viral entry and nuclear migration." (PMID 34765923, 2021). "Thus, IP-10 promotes HIV latent infection of resting memory CD4+ T cells through binding with CXCR3." (PMID 34447368, 2021). "Secondly, HIV can also directly infect resting memory CD4+ T cells, resulting in latent infection." (PMID 34447368, 2021).
latent infection (continued). "In addition, a recent study showed that latent infection in blood CD4+ T cells from HIV-1 infected individuals on suppressive therapy was due to blocks in the post-initiation stages of transcription, including elongation, RNA-capping and splicing." (PMID 34194479, 2021). "Our results from DFV-B infection indicated that EMT CD4+ T cells were less permissive to infection, but once infected were much more likely to establish latency, which supports that EMT CD4+ T cells are the primary targets for latent infection, and highlights the feasibility of our DFV-B system." (PMID 33835029, 2021). "HIV latent infection can also be established by direct infection of resting memory CD4+ T cells." (PMID 34447368, 2021). "We showed that TIM-TAM is involved in regulating latent infection, as viruses carrying a silent mutation disrupting the secondary structure of TIM-TAM resulted in a restriction in establishment of latency in primary CD4+ T-cells." (PMID 34194479, 2021). "The proteins and pathways identified in these studies represent a basis for developing new anti-HIV therapeutic strategies such as new drugs preventing infection of CD4+ cells and viral replication, effective vaccines, “shock and kill” and “block and lock” approaches to cure latent infection." (PMID 32625189, 2020). "Previous studies have demonstrated that both CD4 T cells and CD8 T cells can control acute replication and latent infection of MHV68, whereas CD4 T cell control of acute and latent infection of MHV68 requires IFN-γ that has also been shown to regulate MHV68 reactivation." (PMID 32735617, 2020). "CD4+ T cells undergoing effector-to-memory transition are permissive for HIV-1 latent infection." (PMID 31036079, 2019). "Our data corroborate this view, since rec-MVA induced strong effector CD4+ T cells producing IFNγ which may have been consumed to control the latent infection." (PMID 31921215, 2019). "Although the role of autophagy in the establishment of HIV latent infection in resting CD4+ TCM cells is unknown, many studies have shown that autophagy is essential for generating T memory cells and maintaining its immune function." (PMID 31142734, 2019). "However, the early establishment of latent infection within resting CD4+ T cells and the presence of poorly characterized viral reservoirs in tissues represent major obstacles to a definitive cure for HIV." (PMID 31427605, 2019). "HIV-1 latent infection in resting memory CD4+ T cells is a major barrier to HIV-1 eradication." (PMID 31632965, 2019). "From our last study, we knew HUVEC-stimulated resting CD4+ T cells harbor latent infection." (PMID 30285810, 2018). "We next sought to determine whether PD-1 was differentially expressed on Mtb-specific CD4 T cells in persons with latent infection and active TB disease." (PMID 30233588, 2018). "However, it has been recently documented that the infection of unactivated CD4+ T-cells also occurs, resulting mostly in a latent infection." (PMID 29997630, 2018). "Together, these data show that IL-27 regulates the number and effector functions of MCMV-specific CD4 T cells and could be targeted to enhance control of persistent/latent infection." (PMID 30044874, 2018). "CCL19, CCL21, IL-7, and IL-15 are known to promote latent infection in resting CD4+ T-cells." (PMID 29997630, 2018). "We further demonstrated that EC stimulation can result in latent infection in resting CD4+ T cells." (PMID 30285810, 2018). "Based on all these findings, the second-generation of dual-fluorescence reporter, HIVGKO, is able to more accurately quantify latent infections in primary CD4+ T cells than HIVDuoFluoI, and thus allows for the identification and purification of a larger number of latently infected cells." (PMID 29714165, 2018). "It was reasoned that complementing HIV-1 with Vpx might promote moreefficient infection of primary resting CD4+ T cells, and therefore moreeffective establishment of latent infection." (PMID 28113052, 2017).
latent infection (continued). "In the present study, we asked whether the PI3K signalling pathway, induced by ligation of CCL19 to CCR7, played a key role in the establishment of latent infection in CCL19-treated resting CD4+ T cells." (PMID 27459960, 2016). "Given that R5-tropic HIV are the major transmitted viral strain, and therefore are the main strains that establish HIV latency, we also assessed the impact of increasing R5-tropic HIVNL4.3(AD8).EGFP titre on latent infection of unstimulated and mDC co-cultured resting CD4+ T-cells." (PMID 27383184, 2016). "Other downstream signalling products of chemokine receptor signalling may also impact HIV integration and latent infection of resting CD4+ T cells." (PMID 27459960, 2016). "Interestingly, the cytokine, IL-7, which increases permissibility of resting CD4+ T cells to productive HIV infection, also increased both productive and latent infection in resting CD4+ T cells in our study." (PMID 26067822, 2015). "Therefore we compared monocytes and mDC isolated from healthy donors for their ability to induce latent infection in resting CD4+ T-cells." (PMID 26362311, 2015). "Together these data suggest that SIGLEC 5 or 10 binding to its ligand on the CD4+ T-cell may reduce T-cell activation, reduce productive infection and potentially promote latent infection." (PMID 26362311, 2015). "The mechanisms for establishment and maintenance of latent infection in resting memory CD4+ T-cells remain unclear." (PMID 26362311, 2015). "Additionally, infecting activated CD4+ T cells is more likely to result in productive infection, while infecting resting CD4+ T cells is more likely to result in latent infection." (PMID 26067822, 2015). "Levels of latent infection in untreated CD4+ T cells isolated from both lymphoid tissues were at least 2-fold greater than those observed in untreated CD4+ T cells from peripheral blood, suggesting that CD4+ T cells within lymphoid tissue are more likely to become latently infected." (PMID 26067822, 2015). "Also in agreement with previous findings, resting CD4+ T cells were made more permissive to HIV infection when exposed to the chemokine CCL19, which increases the ability of resting CD4+ T cells to support latent infection." (PMID 26067822, 2015). "Indeed, we found that multifunctional CD4+ T cells, in particular those producing 3 cytokines simultaneously, provided the best discrimination between active and latent infection." (PMID 26339657, 2015). "However, our data demonstrate that CCL19 also increases permissibility to productive infection, although its overall effect on resting CD4+ T cells increases latent infection." (PMID 26067822, 2015). "However, the current drug compositions are not able to completely eliminate the virus, since HIV-1 is capable of maintaining latent infection in stable reservoirs such as resting CD4+ T cells, naive T cells and CD34+ multipotent hematopoietic stem cells." (PMID 26178009, 2015). "Therefore, while activated CD4+ T cells support the most robust infection, latent infection is more likely to occur relative to productive infection in cells that are resting or are transitioning back to a resting state." (PMID 26067822, 2015). "Using primary CD4+ T cells isolated from the blood of uninfected donors, we demonstrate that infecting resting and activated CD4+ T cells with our HIV Duo-Fluo I virus causes both productive and latent infection in the two populations." (PMID 26067822, 2015). "However, we show how productive and latent infection is distributed within resting CD4+ T cells after such treatments." (PMID 26067822, 2015). "In addition, HIV-1 Env has been shown to regulate the establishment of latent infection in resting CD4+ T cells, likely through modulating the functionality of certain cellular pathways." (PMID 25738301, 2015).
latent infection (continued). "The most numerous were toxoplasmosis retinitis by reactivation of preexisting latent infection due to the collapse of the defense capacity (CD4 < 50/μL in 12 patients and < 4/μL in 4 patients), especially since only 3 of the 16 were following the HAART treatment." (PMID 25408764, 2014). "During latent infection expression of viral UL111A (vIL-10) results in down regulation of MHC class II and diminished CD4+ T cell recognition and latent infection of CD34+ bone marrow progenitor cells induces release of cIL-10 and TGFβ which decreases CD4+ T cell IFNγ production and cytotoxicity." (PMID 24130479, 2013). "In HSV-2 infection IFNγ-producing CD4 T cells seem to be essential to establish latent infection." (PMID 23717308, 2013). "The alteration of CCR6 uses by viruses may influence the susceptibility of CD4+ CCR6+ T-cells and dendritic cell subsets in vivo and therefore, is important for viral pathogenesis in establishing latent infections, trafficking, and transmission." (PMID 24009735, 2013). "We first discuss how latent infection can be established following infection of an activated CD4 T-cell that undergoes a transition to a resting memory state and also how direct infection of a resting CD4 T-cell can lead to latency." (PMID 23375003, 2013). "Although multiple reservoirs may exist, the persistence of resting CD4+ T cells carrying a latent infection represents a major barrier to eradication." (PMID 23803414, 2013). "We have previously shown that memory CD4+ T cells and not naïve CD4+ T cells are susceptible to latent infection following chemokine exposure." (PMID 24339779, 2013). "In addition, a cut-off of 37.4% of single-positive TNF-α+ CD4+ T-cells was calculated as the value allowing the best separation between latent infection and active disease (sensitivity of 100% and specificity of 96%)." (PMID 24376464, 2013). "This has been explicitly demonstrated recently in HIV-1 latent infection of resting CD4 T cells." (PMID 22640593, 2012). "MDV is an oncovirus using CD4+ T cell as a target for latent infection and transformation, which may have interactions with the CD4 gene at the epigenetic level." (PMID 21645322, 2011). "Given the low frequency of latently infected memory CD4+ T-cells in vivo, robust in vitro models of HIV latency in primary CD4+ T-cells are urgently needed to better understand the establishment and maintenance of latency as well as identify novel strategies to reverse latent infection." (PMID 21992606, 2011). "Hence, while only CD8+ T cells can rapidly recognise new infections, only CD4+ T cells will recognise latent infections in which viral gene expression is extinguished yet a pool of viral antigens remains." (PMID 20019813, 2009). "Hence, newly-infected cells are rapidly visible only to the CD8 response; by contrast, latent infections, in which viral gene expression has been extinguished yet viral proteins persist, will remain visible to CD4+ T cells." (PMID 20019813, 2009). "In agreement with previous reports, the in vitro latent infection of resting CD4+ T lymphocytes generated a pool of infected cells in the preintegration phase of HIV-1 latency able to integrate some extrachromosomal HIV-1 DNA forms into their genome after polyclonal stimulation." (PMID 17727722, 2007). "In addition, the gHgL-mRNA vaccine was able to elicit a gHgL-specific CD4+ T-cell response in mice that might have partially contributed to the observed in vivo protection against MHV68 latent infection." (PMID 40872916, 2025). "Therefore, MDV may preferentially establish latent infection in activated CD4+ T-cells expressing PD-1 and transform them." (PMID 40430752, 2025). "We and others have demonstrated that while resting CD4 + T cells were poorly infected by themselves, after being stimulated by endothelial cells (EC), they can be directly infected while remaining in a resting state, resulting in substantially higher productive and latent infections." (PMID 37202790, 2023).
latent infection (continued). "HIV leads to a decrease in the number of T CD4 lymphocytes with a CD4 cell count usually below 200 cells/mL, and less than 100 cells/mL, and in 90% of these patients, the infection represents reactivation of a previously acquired subclinical or latent infection." (PMID 37685370, 2023). "Thus, we also tested whether CD2 prestimulation can block latent infection of memory CD4 T cells by R5 virus." (PMID 34765923, 2021). "Finally, novel small molecule inhibitors of CD2 may need to be developed and tested for inhibiting HIV latent infection of blood CD4 T cells." (PMID 34765923, 2021). "However, in the Wild-type model, most of the latent infection happens during the cell-to-cell transmission, which may also explain why this model appears more similar to CD4+ T cells from ART-suppressed individuals." (PMID 33253324, 2020). "Moreover, CD4+ T cells undergoing effector-to-memory transition have been reported to be “primed” for HIV latent infection due to the transient upregulation of HIV co-receptor CCR5 and concomitant gene expression down-regulation, which silences the incoming provirus." (PMID 31454973, 2019). "Therefore, dual‐fluorescent reporter viruses with the EF1α promoter may underestimate the frequency of latent infection in resting CD4+ T cells." (PMID 31855322, 2019). "Killing HIV-infected resting CD4+ T cells early after viral entry before the reverse transcription step would abrogate both abortive and latent infection and would thus help to decrease CD4+ T cell depletion and inflammation, and could affect the size of the latent viral reservoir." (PMID 30943397, 2019). "In addition, we were very intrigued by the finding that LEC could induce significant infection in memory CD4+ T cells, both productively and in latent infection." (PMID 30285810, 2018). "Here we asked whether different antigen presenting cells (APC), including subpopulations of DC and monocytes, were able to induce post-integration latent infection in resting CD4+ T-cells, and examined potential cell interactions that may be involved using RNA-seq." (PMID 26362311, 2015). "Additionally, infecting untreated total lymphoid cell populations results in more latent infection than when infecting purified untreated CD4+ T cells from the same tissue, suggesting that co-culture of CD4+ T cells with other lymphoid cells promotes latent infection." (PMID 26067822, 2015). "Our results show that both CD4+ and CD8+ T cells experience significant changes in subset populations during latent infection." (PMID 39807873, 2025). "While both HSV-1-specific CD4+ and CD8+ T cells are found in the TG, CD8+ T cells are the dominant adaptive immune cell positioned to act against HSV-1 during latent infection." (PMID 40431612, 2025). "The possibility that similarreceptor molecules on CD4+ T cells enable PEDV invasion and theestablishment of latent infections requires further investigation." (PMID 40094365, 2025). "However, the presence of latent infection in activated CD4 + T cells remains unclear." (PMID 37202790, 2023). "HIV is an extremely harmful virus, HIV mainly infects a variety of immune cells with CD4+ T and chemokine receptors CXCR4/CCR5 on their surface, making them in a latent infection state." (PMID 37108519, 2023). "Rather, because we show HIV replicates in Fiebig I in resting CD4+ T cells as essentially the only target population available, we hypothesized that the latently infected cell populations in Fiebig I LNs are also directly established as latent infections in resting CD4+ T cells." (PMID 37733443, 2023). "Here we investigated responses to RIG-I agonists and type 1 interferon in a variety of different in vitro models of HIV latent infection or virologic suppression, including a model of HIV suppression in primary CD4 + T cells." (PMID 35804422, 2022).